G6PD (glucose-6-phosphate dehydrogenase)
Diseases named in the same sentence as G6PD in open-access papers (continued):
Sharing a sentence is not in itself a finding about the gene and the disease.
G6PD deficiency (continued). "The results showed that while the Kinh ethnic group had the highest prevalence of G6PD deficiency (∼60%), the Thai ethnic group carried the lowest G6PD distribution compared to the others." (PMID 35845714, 2022). "This study aims to determine the prevalence of G6PD deficiency and the types of G6PD mutation in the southern Thai population." (PMID 36248708, 2022). "A total of 42 G6PD deficiency subjects (14 males and 28 females) were analyzed for eight types of G6PD gene mutation by DiaPlexCTM G6PD Genotyping Kit (Asian type) and further confirmation by PCR-RFLP in the first three common mutations." (PMID 36248708, 2022). "Vicine-convicine also causes favism, a severe form of hemolytic anemia, in humans who have an X chromosome-inherited glucose-6-phosphate dehydrogenase (G6PD) deficiency." (PMID 36552629, 2022). "Although phagocytes from most G6PD-deficient patients have normal bactericidal activity, rare cases with severe G6PD deficiency have been reported to be prone to infection." (PMID 36353116, 2022). "Glucose-6-phosphate dehydrogenase deficiency (G6PDd) is an X-linked genetic disorder caused by mutations in the G6PD gene on X-chromosome (Xq28)." (PMID 36076204, 2022). "The prevalence of G6PD deficiency and G6PD variants has been reported in the southern Thai population." (PMID 36248708, 2022). "In particular, donors of semen for external use in the Guangxi and Guangdong provinces in south China, which have a high incidence of thalassemia and G6PD deficiency, should be tested for the α-like, β-like globin genes and G6PD gene." (PMID 36204111, 2022). "There are more than 400 G6PD mutations, of which 186 variants have shown to be linked to G6PD deficiency by decreasing the activity or stability of the enzyme." (PMID 36381187, 2022). "Four G6PD gene mutations were found in the diabetes with G6PD deficiency patients: c.1376G > T, c.1388G > A, c.95A > G, and c.871G > A, all of which were genes with high frequency of G6PD deficiency in Guangdong Province." (PMID 35313968, 2022). "The G6PD deficiency, one of the most common enzymopathies reported worldwide, is usually regarded as genetically determined by hereditary defects in the G6PD gene." (PMID 36431166, 2022). "Several quantitative and qualitative assays are available for diagnosing G6PD deficiency, and most tests measure enzymatic activity in lysate from all RBCs, which reflects the overall G6PD activity in a blood sample." (PMID 35840819, 2022). "This study aims to provide more information on G6PD deficiency prevalence and the G6PD variants in the southern Thai population." (PMID 36248708, 2022). "Naphthalene-induced acute hemolysis with methemoglobinemia is a rare condition that commonly affects patients with glucose-6-phosphate dehydrogenase (G6PD) deficiency." (PMID 35494903, 2022). "Although there have been many reports of G6PD deficiency status and its mutations in malaria patients living in the Southeast Asia, data on the haematological parameters of G6PD and other erythrocytic mutations including PK in malaria patients are limited." (PMID 36038921, 2022). "G6PD deficiency in RBCs results in clinical manifestations stemming from the inability of G6PD-deficient RBCs to deal with ROS." (PMID 35685917, 2022). "Males are hemizygous for G6PD deficiency, showing either normal G6PD activity levels or G6PD deficiency depending on the G6PD allele they carry (wild-type or G6PD variant)." (PMID 35529053, 2022). "Hypomorphic Glucose 6-P dehydrogenase (G6PD) alleles, which cause G6PD deficiency, affect around one in twenty people worldwide." (PMID 36231003, 2022). "Among the 957 neonates with abnormal G6PD enzyme activity, the prevalence of G6PD deficiency in Wuhan was calculated as 0.22%." (PMID 36212142, 2022). "The %bright cells values between G6PD normal and G6PD deficiency in both female (97.5±2.4 and 49.5±22.7, respectively) and male samples (96.7±2.4 and 17.8±23.2, respectively) were significantly different (p<0.01)." (PMID 35840819, 2022).
G6PD deficiency (continued). "The only available class of drugs with hypnozoitocidal activity are the 8-aminoquinoline compounds (primaquine and tafenoquine), which cause severe haemolysis in individuals with glucose-6-phosphate dehydrogenase (G6PD) deficiency." (PMID 36145477, 2022). "In Sardinia (Italy), a major Mediterranean island, G6PD deficiency represents a real public health issue, since over 10% of the population shows the G6PD-deficient genotype." (PMID 35743352, 2022). "Neonates are often routinely screened for G6PD deficiency by detecting G6PD enzyme activity with a rapid fluorescent spot test." (PMID 36353116, 2022). "In this study, we successfully identified 13 G6PD variants related to G6PD deficiency in Northern Vietnam by Sanger sequencing." (PMID 35845714, 2022). "Six (19.35%) female patients and sixteen (39.02%) male patients had both G6PD c.202G > A/c.376A > G mutations concomitantly c.202G > A and c.376A > G are responsible for the majority of the observed prevalence of G6PD deficiency in Brazil." (PMID 35527254, 2022). "Because female individuals with heterozygous G6PD deficiency typically exhibit a wide range of G6PD activity levels owing to random X-inactivation, phenotypic testing alone is ineffective at identifying them." (PMID 36339627, 2022). "Individuals with G6PD deficiency and heterozygous females with normal G6PD activity (i.e., all individuals with pathogenic G6PD variants) are at risk of developing hemolytic anemia under increased oxidative challenge." (PMID 36212124, 2022). "Although there are numerous reticulocytes in the circulation during the hemolytic crisis as a result of G6PD deficiency, their G6PD activity cannot increase the total blood G6PD activity to the normal level." (PMID 36419023, 2022). "G6PD deficiency is caused by G6PD gene mutation, resulting in varying degrees of enzyme deficiency and protein variation, which is related to various clinical subtypes." (PMID 36160421, 2022). "Heterozygous females can achieve the same degree of G6PD deficiency and can be susceptible to the same pathophysiological phenotype present in G6PD-deficient males." (PMID 36231003, 2022). "We included a total of 3231 qualified sperm donors: all donors underwent primary screening for thalassemia and glucose-6-phosphate dehydrogenase (G6PD) deficiency." (PMID 36204111, 2022). "Flow cytometry can be used to screen patients with G6PD deficiency, and reliably and efficiently identify heterozygous and homozygous females, and hemizygous males based on cellular G6PD activity." (PMID 35840819, 2022). "G6PD deficiency has been recognized as a common inherited enzymopathy where G6PD Viangchan (*51) and G6PD Mahidol variant (*31) is highly prevalent in Thais." (PMID 35176049, 2022). "Certain clinical indications and treatments such as the use of rasburicase in cancer therapy and 8-aminoquinolines for Plasmodium vivax malaria treatment would benefit from a point-of-care test for glucose-6-phosphate dehydrogenase (G6PD) deficiency." (PMID 34543346, 2021). "Simultaneous evaluation of G6PD activity and genotype will advance our knowledge of the genotype-phenotype correlations in G6PD deficiency." (PMID 34659341, 2021). "The prevalence of G6PD deficiency in people living in a malaria endemic area in Thailand, namely, Tha Song Yang District, Tak Province, was determined by G6PD activity assay (WST-8)." (PMID 33879156, 2021). "The most commonly used screen for G6PD deficiency is the qualitative G6PD fluorescent spot test (FST), which detects the naturally fluorescent NADPH." (PMID 33891587, 2021). "No serious adverse events related to hemolysis have occurred in G6PD normal individuals with >70% activity; however, in a malaria prophylaxis, clinical efficacy trial two females with G6PD deficiency were misclassified as G6PD normal." (PMID 33306921, 2021). "In humans, G6PD deficiency is the most common enzyme deficiency due to an X-linked mutation associated with reduced G6PD enzymatic activity." (PMID 33995067, 2021).
G6PD deficiency (continued). "G6PD Aures causing mild G6PD deficiency associated with favism was firstly discovered in Algeria in 1993." (PMID 33628497, 2021). "Other erythrocyte genetic abnormalities, such as α-thalassemia and glucose-6-phosphate dehydrogenase (G6PD) deficiency, can also confer protection against malaria and coexist in populations affected by HbS in malaria endemic areas." (PMID 33842387, 2021). "Since severe acute haemolytic anaemia can be triggered by G6PD deficiency, addressing the prevalence and molecular characterization of G6PD mutations in the Lao Theung ethnic group is an important public health issue." (PMID 33413378, 2021). "The STANDARD G6PD Test is a promising tool to aid in the identification of G6PD deficiency in Brazil." (PMID 34383774, 2021). "A quantitative G6PD assay was done, and the level was low, which confirmed the diagnosis of G6PD deficiency." (PMID 34964759, 2021). "The severity of hemolytic anemia varies among individuals with G6PD deficiency, depending on the genetic variant in the G6PD gene; this makes the diagnosis of the condition more challenging in some cases." (PMID 34178542, 2021). "We documented the prevalence of inherited hematological disorders in the Central region as follows: 0.1% SCD, 7.0% SCT, 45.7% α-thalassemia trait, 20.4% G6PD deficiency in males, and 29.0% G6PD female carriers." (PMID 34335138, 2021). "G6PD deficiency is induced by a mutation in the G6PD gene (OMIM 305900) located on the long arm of the X chromosome (Xq28)." (PMID 34200975, 2021). "We determined the profile of G6PD deficiency in Xiamen city, including the prevalence, G6PD variant spectrum, and genotype-phenotype correlations, and also revealed the effect of temperature during sample transport on screening accuracy." (PMID 34659341, 2021). "There were only 7 patients with G6PD deficiency and 60 patients with normal G6PD taking clopidogrel alone with complete hematological data in our analyses." (PMID 34369077, 2021). "Over 200 G6PD variants have been identified, which form genotypes associated with differences in the degree of G6PD deficiency and vulnerability to haemolysis." (PMID 33879156, 2021). "The second most frequently observed African-type G6PD genotype associated with G6PD deficiency was Betica-Selma or A376G/T968C double mutation (12/996; 1.2%, 95% CI (0.6–2.1%); 7 males and 5 homozygous females)." (PMID 34451395, 2021). "For example, while G6PD deficiency is common in Africans and Chinese, the A allele alone explains nearly all G6PD deficiencies in Africans, whereas seven G6PD alleles contribute to the deficiency in HK Chinese." (PMID 33600428, 2021). "Glucose-6-phosphate dehydrogenase (G6PD) deficiency is an inherited genetic defect and the most common enzymopathy, affecting approximately 500 million people worldwide with more than 200 variants have been identified." (PMID 33879156, 2021). "The most common syndrome causing drug-induced haemolytic anaemia is the glucose-6-phosphate dehydrogenase (G6PD) deficiency." (PMID 33995067, 2021). "Malaria was diagnosed using microscopy whilst G6PD deficiency was determined using restriction fragment length polymorphisms at position 376 and 202 of the G6PD gene." (PMID 34570821, 2021). "The STANDARD G6PD Test is a novel, point-of-care test for G6PD deficiency that provides a numeric measurement of G6PD activity normalized by hemoglobin." (PMID 34383774, 2021). "This study provides the first P.berghei transcriptome data in the context of G6pd deficiency and indicates its unique genes expression changes in G6pd deficiency." (PMID 34456927, 2021). "This study characterizes the molecular heterogeneity of G6PD variants causing G6PD deficiency in Thai children." (PMID 33628497, 2021). "These drugs have warning labels for use in individuals with glucose-6-phosphate dehydrogenase (G6PD) deficiency." (PMID 34302047, 2021).
G6PD deficiency (continued). "The USA Kernicterus Registry has reported that CHAs, particularly glucose-6-phosphate dehydrogenase (G6PD) deficiency and hereditary spherocytosis (HS), are among the leading root causes of kernicterus, second only to ABO incompatibility." (PMID 34573891, 2021). "The aim of this study is to determine the cut‐off value of glucose‐6‐phosphate dehydrogenase (G6PD) activity and the mutation spectrum of G6PD gene in neonates with G6PD deficiency at Ningbo." (PMID 34762759, 2021). "Among enzymopathies, we also identified 3 cases with undiagnosed G6PD deficiency, an heterozygous woman and two men with G6PD variants associated with chronic hemolysis, conditions in some cases underdiagnosed." (PMID 34093240, 2021). "Although the females with heterozygous G6PD mutation have sufficient enzyme activity, they can pass an X-linked G6PD mutation to all of their sons and daughters along with a risk of developing the symptoms associated with a severe G6PD deficiency." (PMID 33413378, 2021). "Examination of G6PD activity revealed that both the infant and her asymptomatic mother were heterozygous for G6PD deficiency." (PMID 33925963, 2021). "Rarely, methemoglobinemia can also happen because of fava bean ingestion in patients with glucose-6-phosphate dehydrogenase (G6PD) deficiency." (PMID 34964759, 2021). "The first-time assessment of G6PD deficiency prevalence and molecular characterization of G6PD mutations in the Lao Theung population were performed in this study." (PMID 33413378, 2021). "If there was an adverse effect reported, such as black tea coloured urine after administration of PQ in those with glucose-6-phosphate dehydrogenase (G6PD) deficiency, treatment would be stopped immediately." (PMID 33407512, 2021). "In the subsequent diagnosis, 243 newborns were tested using the NBT G6PD/6PGD assay, and 200 (172 males and 28 females) of them were diagnosed with G6PD deficiency, for a Positive Predictive Value (PPV) of 82.30% (200/243)." (PMID 34659341, 2021). "Glucose-6-phosphate dehydrogenase (G6PD) deficiency is an X-linked recessive hereditary red blood cell disorder." (PMID 33536585, 2021). "Among them, we found 0.3% were compound heterozygotes, 2.7% were homozygotes, 68.4% were heterozygotes for five variants of severe G6PD deficiency, and the rest (28.6%) were G6PD-normal." (PMID 34270547, 2021). "G6PD deficiency is caused by mutation in the G6PD gene (OMIM 305900), located on the long arm of the X chromosome (Xq28)." (PMID 33628497, 2021). "Favism, for example, is a rare disease caused by Glucose-6-phosphate dehydrogenase (G6PD) deficiency and G6PD deficient cells are more vulnerable to SARS-CoV-2 infection." (PMID 33937170, 2021). "We identified nine variants, of which four are potentially deleterious to G6PD function, and one (rs1050828) that is known to cause G6PD deficiency." (PMID 34302047, 2021). "The STANDARD G6PD Test is a promising tool to aid in detecting G6PD deficiency at the point of care in Brazil." (PMID 34383774, 2021). "For the hyperbilirubinemia group, neonates with G6PD deficiency had a higher bilirubin level compared to those with normal G6PD." (PMID 34895177, 2021). "Now out of those with appropriate birth weight at term, 1 had Glucose-6-Phosphate dehydrogenase (G6PD) deficiency, 1 had Down's syndrome and high TSH of 34.3 mIU/l." (PMID 34494465, 2021). "The pathogenic gene of G6PD deficiency is G6PD, which is located on Xq28 and consists of 13 exons and 12 introns." (PMID 34659341, 2021). "Our study reveals the immune changes in the host of G6pd deficiency during malaria and showed the role of G6pd defect in suppressing the immune response." (PMID 34456927, 2021). "Unfortunately, its deployment is limited because of concerns over hemolytic effects in patients with glucose-6-phosphate dehydrogenase (G6PD) deficiency." (PMID 34724729, 2021).
G6PD deficiency (continued). "In conclusion, this study characterizes the molecular heterogeneity of G6PD variants causing G6PD deficiency among Thai children." (PMID 33628497, 2021). "Hereditary anemia is caused by various hematological genetic disorders and has various manifestations, such as sickle cell disease (SCD), Fanconi anemia (FA), glucose-6-phosphate dehydrogenase (G6PD) deficiency, and thalassemia." (PMID 34200975, 2021). "Glucose-6-phosphate dehydrogenase (G6PD) deficiency is the most common X-linked inherited erythroenzymopathy in Thailand." (PMID 33628497, 2021). "Fourteen additional patients were described: five with paroxysmal nocturnal hemoglobinuria and 9 with previously undiagnosed glucose-6-phosphate dehydrogenase (G6PD) deficiency uncovered in context of acute hemolysis." (PMID 33912067, 2021). "Results from this study highlight the heterogeneity of G6PD level in the Sudanese population, and the good performance of the CareStart test for detection of moderate-to-severe G6PD deficiency." (PMID 34699526, 2021). "Most of the studies that included detailed haematologic changes associated with G6PD deficiency were conducted in populations where G6PD Mahidol is predominant." (PMID 33790795, 2021). "G6PD deficiency is mostly caused by a single nucleotide mutation that gives rise to an amino acid substitution in an exon of the G6PD gene, resulting in reduced enzyme activity and stability." (PMID 33413378, 2021). "The varying degree of G6PD deficiency among malaria-infected national groups supports the strongly recommend G6PD testing by the National Malaria Control Program and the subsequent safe treatment of P. vivax for radical cure." (PMID 34108049, 2021). "The findings show that the STANDARD G6PD Test performed equivalently to the reference test in its ability to diagnose G6PD deficiency at the point of care." (PMID 34383774, 2021). "Two CZS-affected individuals, CZS_8 and CZS_27, both females, carried the variant rs1050828 (MAF gnomAD: 0.009) in G6PD gene associated with hemolytic anemia due to G6PD deficiency (OMIM #300908) in an X-linked dominant manner." (PMID 34125832, 2021). "This fold increase was doubled in diabetic patients with G6PD deficiency and was significantly higher than in G6PD-deficient subjects and diabetics with sufficient G6PD (p<0.001)." (PMID 34949182, 2021). "We also scored eight polymorphisms in G6PD that have been functionally associated with various degrees of G6PD deficiency and found that 32% of the study population carried at least one, including 12 of the 20 donors with hemoglobinopathies." (PMID 34553687, 2021). "The gold standard to diagnose G6PD deficiency is a quantitative spectrophotometric assay that determines G6PD activity per gram of Hb (normal values 7–10 U/g Hb)." (PMID 34573891, 2021). "Based on hospital admission records, the authors found that the proportion of coronary artery disease, but not cerebrovascular disease, was significantly less frequent in men with G6PD deficiency (A and A– variants) than in those with normal G6PD (B variant)." (PMID 34007401, 2021). "G6PD was discovered in 1956, and to date, G6PD deficiency has influenced around 130–220 million people around the world individually, and more than 200 mutations have been noted." (PMID 34762759, 2021). "One participant was hemizygote for a variant (c.1388G>A) in the G6PD gene associated with the classic glucose-6-phosphate dehydrogenase deficiency (G6PD)." (PMID 34794485, 2021). "G6PD deficiency is caused by a mutation(s) in the G6PD gene with over 200 variants reported worldwide, and each mutation has a different effect that results in a wide range of clinical manifestations." (PMID 34934109, 2021). "The elimination of Plasmodium vivax malaria requires 8-aminoquinolines, which are contraindicated in patients with glucose-6-phosphate dehydrogenase (G6PD) deficiency due to the risk of acute haemolytic anaemia." (PMID 34353361, 2021).